CTNNBIP1 (catenin beta interacting protein 1)
Description:
Prevents the interaction between CTNNB1 and TCF family members, and acts as a negative regulator of the Wnt signaling pathway.
Synonyms: ICAT; MGC15093
Tractability: PROTAC: ubiquitination databases record sites on it.
Gene: Protein-coding gene on chromosome 1 (9,848,269 to 9,910,368, reverse strand). Ensembl gene ENSG00000178585.
Subcellular location: Cytoplasm; Nucleus
Subcellular location (Human Protein Atlas): Cytosol; Nucleoplasm
Pathways (Reactome):
Signal Transduction: Deactivation of the beta-catenin transactivating complex
Gene Ontology:
Molecular function: armadillo repeat domain binding; beta-catenin binding; protein binding; transcription coactivator binding; transcription regulator inhibitor activity
Biological process: canonical Wnt signaling pathway; negative regulation of canonical Wnt signaling pathway; negative regulation of mesenchymal cell proliferation; negative regulation of protein-containing complex assembly; negative regulation of transcription by RNA polymerase II; negative regulation of transcription initiation by RNA polymerase II; positive regulation of monocyte differentiation; positive regulation of osteoblast differentiation; regulation of vascular permeability involved in acute inflammatory response; negative regulation of Wnt signaling pathway; negative regulation of cell population proliferation; negative regulation of smooth muscle cell proliferation
Cellular component: beta-catenin destruction complex; cytoplasm; cytosol; nucleus; nucleoplasm; beta-catenin-ICAT complex
Genetic constraint (gnomAD): Loss-of-function variants: 7 observed, 10.22 expected, observed/expected ratio (o/e) 0.69, 90% interval 0.39 to 1.28. The synonymous counts are far from expectation, so gnomAD's model fits this gene poorly and the ratio says little. Missense variants: 101 observed, 101.85 expected, observed/expected ratio (o/e) 0.99, 90% interval 0.84 to 1.17. Synonymous variants: 58 observed, 40.14 expected, observed/expected ratio (o/e) 1.45, 90% interval 1.17 to 1.79.
Homologues: Orthologues: chimpanzee CTNNBIP1 (100% identical), pig CTNNBIP1 (99% identical), rat Ctnnbip1 (99% identical), mouse Ctnnbip1 (98% identical), rabbit CTNNBIP1 (98% identical), guinea pig CTNNBIP1 (93% identical), zebrafish ctnnbip1 (88% identical), dog CTNNBIP1 (81% identical), Caenorhabditis elegans ZK1248.19 (19% identical). Paralogues in human: LZIC (36% identical).
Diseases named in the same sentence as CTNNBIP1 in open-access papers:
CTNNBIP1 is named in the same sentence as 47 diseases in open-access papers, as found by Europe PMC text mining. Sharing a sentence is not in itself a finding about the gene and the disease. The quoted sentences say what the papers report.
glioma (12 papers, 2015 to 2025). A benign or malignant brain and spinal cord tumor that arises from glial cells (astrocytes, oligodendrocytes, ependymal cells). "This elevation aids circDLC1 in its competitive binding with miR-671-5p, which in turn supports the transcription of Catenin Beta Interacting Protein 1 (CTNNBIP1) and ultimately inhibits the excessive growth of glioma cells." (PMID 38474421, 2024). "Consistently, we found that CTNNBIP1 silencing attenuated the inhibitory effect of circDLC1 overexpression on glioma cell proliferation." (PMID 35474040, 2022). "Briefly, METTL3 suppressed glioma cell malignant proliferation via the circDLC1/miR-671-5p/CTNNBIP1 axis in vivo." (PMID 35474040, 2022). "The target genes of miR-671-5p were predicted and intersected, in which CTNNBIP1 is poorly expressed in glioma." (PMID 35474040, 2022). "We demonstrated that miR-671-5p expression was elevated and CTNNBIP1 expression was declined in glioma tissues and cells, and circDLC1 promoted CTNNBIP1 transcription by binding to miR-671-5p." (PMID 35474040, 2022). "Briefly, METTL3 suppressed the glioma cell proliferation via the circDLC1/miR-671-5p/CTNNBIP1 axis in vivo." (PMID 35474040, 2022). "CTNNBIP1 downregulation is related to unfavorable prognosis, high histological grade, and advanced glioma progression." (PMID 35474040, 2022). "Briefly, CTNNBIP1 silencing attenuated the inhibitory effect of circDLC1 overexpression on glioma cell proliferation." (PMID 35474040, 2022). "METTL3 overexpression repressed the malignant proliferation of glioma via circDLC1/miR-671-5p/CTNNBIP1 in vivo." (PMID 35474040, 2022). "In the future, we will verify the effect of CTNNBIP1 protein level on glioma cell proliferation and explore other possible mechanisms of circDLC1." (PMID 35474040, 2022). "Collectively, METTL3-mediated m6A modification upregulated circDLC1 expression, and circDLC1 promoted CTNNBIP1 transcription by sponging miR-671-5p, thus repressing the malignant proliferation of glioma." (PMID 35474040, 2022). "miR-671-5p expression was negatively correlated with circDLC1 and CTNNBIP1 expression in glioma tissues, and CTNNBIP1 expression was positively correlated with circDLC1 expression (p < 0.05)." (PMID 35474040, 2022). "This study elucidated that METTL3-mediated circDLC1 promoted CTNNBIP1 transcription by sponging miR-671-5p, thus repressing the malignant proliferation of glioma cells." (PMID 35474040, 2022). "Negative regulation of CTNNBIP1 correlates with higher grades of glioma." (PMID 41031155, 2025). "Finally, we found that miR-671-5p expression was elevated and CTNNBIP1 expression was reduced in glioma tissues and cells (p < 0.05)." (PMID 35474040, 2022). "Then, we verified the regulatory effect of CTNNBIP1 on glioma cells." (PMID 35474040, 2022). "CTNNBIP1 serves as a tumor suppressor and is demonstrated to be diminished in glioma." (PMID 35474040, 2022). "Interestingly, CTNNBIP1 has been previously confirmed to be a direct target of miR-215-5p in various diagnoses, including human glioma, diabetic nephropathy, or atherosclerosis, and promoting the tumor growth through Wnt/β-catenin signaling pathway." (PMID 33255928, 2020). "Additionally, CTNNBIP1, a direct target of miR-215, was decreased in glioma compared to adjacent normal tissue." (PMID 26317904, 2015). "It promotes TGF-β1-induced oncogenesis by suppressing CTNNBIP1 in glioma." (PMID 26317904, 2015). "Here, we also found decreased expression of CTNNBIP1, increased β-catenin phosphorylation, and increased expression of α-SMA and fibronectin in glioma tumor tissue." (PMID 26317904, 2015). "In addition, we only detected the effect of the change of CTNNBIP1 transcription level on the malignant proliferation of glioma cells, and the effect of the change of CTNNBIP1 protein level is not clear." (PMID 35474040, 2022).
breast carcinoma (5 papers, 2016 to 2021). "Consistent with our findings, a low expression of CTNNBIP1 has been found in human melanomas, breast cancer, and glioblastoma." (PMID 31766223, 2019).
colorectal cancer (4 papers, 2013 to 2025). A primary or metastatic malignant neoplasm that affects the colon or rectum. "We have shown that E2 promoter binding factor 1 (E2F1) suppresses Wnt/β-catenin activity through transactivation of β-catenin interacting protein 1 (CTNNBIP1), also known as inhibitor of β-catenin and TCF4 (ICAT) in human colorectal cancers." (PMID 32326181, 2020). "In support of this conclusion, it was recently reported that E2F1 plays a tumor suppressor role in colorectal cancer by activating CTNNBIP1 and inhibiting β-catenin activity." (PMID 23554908, 2013).
epithelial ovarian cancer (4 papers, 2015 to 2024). "A study of the associations between the SNPs in CTNNBIP1 gene and the platinum treatment response of the Han Chinese patients suffering from epithelial ovarian cancer discovered this association for rs935072, located in CTNNBIP1 3′UTR." (PMID 36430200, 2022). "This conclusion is confirmed by the fact that an overexpression of CTNNBIP1 sensitizes ovarian cancer cells to platinum therapy." (PMID 36430200, 2022). "Further functional experiments confirmed that the overexpression of CTNNBIP1 sensitized ovarian cancer cell to cisplatin treatment." (PMID 33123276, 2020). "Further in vitro experiments demonstrated that overexpression of CTNNBIP1 sensitized ovarian cancer cells to platinum treatment." (PMID 33123276, 2020). "We further found that overexpression of CTNNBIP1 sensitized ovarian cancer cells to platinum treatment." (PMID 33123276, 2020). "Here, we reported a novel regulatory mechanism of CTNNBIP1 activation, thereby uncovering a potential chemotherapeutic target for ovarian cancer treatment." (PMID 33123276, 2020). "To further explore the effect of CTNNBIP1 on chemotherapy sensitivity of ovarian cancer, we treated IGROV1 and OVCAR-8 cell lines selectively overexpressing CTNNBIP1 and their corresponding control cells with different concentrations of cisplatin for 48 h." (PMID 33123276, 2020). "Finally, additional in vivo studies are required to confirm our observed mechanism of CTNNBIP1 in platinum treatment response of ovarian cancer." (PMID 33123276, 2020). "Another genetic variant, CTNNBIP1 rs935072, is implicated in chemoresistance by altering the binding strength of miR-27a-3p to the CTNNBIP1 3′UTR, consequently affecting CTNNBIP1 mRNA expression levels in epithelial ovarian cancer patients." (PMID 38890669, 2024). "However, no studies explored the role of CTNNBIP1 SNPs in treatment response in ovarian cancer patients." (PMID 33123276, 2020).
liver cancer (4 papers, 2013 to 2021). An epithelial or non-epithelial malignant neoplasm that arises from the liver. "LINC00210 activated Wnt/β-catenin signaling through interacting with CTNNBIP1 and blocking the combination between CTNNBIP1 and β-catenin, so as to promoting the self-renewal and propagation of liver cancer." (PMID 34345203, 2021). "High expression of lncRNA linc00210 is detected in liver cancer and contributes to tumor progression by driving the activation of Wnt/β-catenin pathway in a catenin beta interacting protein 1 (CTNNBIP1)-dependent manner." (PMID 30782188, 2019).
melanoma (4 papers, 2015 to 2022). A malignant, usually aggressive tumor composed of atypical, neoplastic melanocytes. "Specifically, the decreased CTNNBIP1 expression levels are present in human malignant melanomas." (PMID 31766223, 2019). "Furthermore, the ectopic expression of CTNNBIP1 has been found to promote the colonization of melanoma cells into the lungs of nude mice." (PMID 31766223, 2019).
papillary thyroid cancer (4 papers, 2018 to 2023). "And overexpression of circRNA_102171 has been reported to promote the occurrence and progression of papillary thyroid carcinoma (PTC) by activating the Wnt/β-catenin pathway in a CTNNBIP1-dependent manner." (PMID 36755291, 2023). "CircRNA_102171 drives papillary thyroid cancer cell proliferation, migration and invasion via activating CTNNBIP1-dependent β-catenin pathway." (PMID 31703640, 2019).
diabetic nephropathy (3 papers, 2013 to 2020). "Taken together, our findings indicate that miR-215 plays an essential role in MC phenotypic transition by regulating the CTNNBIP1/β-catenin pathway, which is related to the pathogenesis of diabetic nephropathy." (PMID 23554908, 2013). "Taken together, our findings demonstrate that miR-215 plays an essential role in diabetic nephropathy pathogenesis by regulating the CTNNBIP1/β-catenin pathway and further suggest that miR-215 is a potential therapeutic target for diabetic nephropathy." (PMID 23554908, 2013).
hepatocellular carcinoma (3 papers, 2018 to 2022). A malignant tumor that arises from hepatocytes. "Further, it was observed that overexpression of miR-424-5p causes a reversal of EMT status, induces anoikis, and suppresses the tumorigenicity of hepatocellular carcinoma by targeting beta-catenin-interacting protein 1 (CTNNBIP1, also known as ICAT), an endogenous β-catenin repressor." (PMID 33435156, 2021).
lung adenocarcinoma (3 papers, 2018 to 2020). A carcinoma that arises from the lung and is characterized by the presence of malignant glandular epithelial cells. "miR-214 also contributes to stemness of cancer stem-like cells by targeting catenin beta interacting protein 1 (CTNNBIP1) in lung adenocarcinoma." (PMID 33614495, 2020). "For example, CTNNBIP1 downregulation promotes progression of lung adenocarcinomas." (PMID 30424816, 2018). "To validate whether the epigenetic silencing of the CTNNBIP1 gene is involved in lung cancer, we first analyzed a cohort of patients with lung adenocarcinoma tumors, obtained from the GSE66836 and GSE66863 projects, and stored in the Gene Expression Omnibus (GEO) database." (PMID 31766223, 2019). "CTNNBIP1 is revealed to be a target gene of miR-214, and is negatively correlated with longer overall survival in lung adenocarcinoma patients." (PMID 33614495, 2020).
lung carcinoma (3 papers, 2019 to 2022). "Our findings using various cellular models show, for the first time, that a loss of CTNNBIP1 brings about an increase in the cell motility of lung cancer cells." (PMID 31766223, 2019). "The results showed that lower levels of CTNNBIP1 were associated with an overall poorer prognosis and a reduced relapse-free survival when 204 lung cancer patients from the GSE31210 project were analyzed (p = 0.011 and p = 0.002, respectively)." (PMID 31766223, 2019). "Furthermore, using various lung cancer cell lines, we confirmed that the epigenetic silencing of CTNNBIP1 is linked to hypermethylation by 5-aza-dC treatment." (PMID 31766223, 2019). "Importantly, the low expression of CTNNBIP1 was also significantly associated with an upward trend in the pathological stage of the lung cancer patients (p = 0.006)." (PMID 31766223, 2019). "MiR-1288–3p is reported to reduce the expression of CTNNBIP1, spurring cell migration in lung cancer." (PMID 35242169, 2022). "To verify the role of CTNNBIP1 in the transcriptional regulation of β-catenin/TCF in lung cancer, we examined the effect of ectopically-expressed CTNNBIP1s that have low levels of expression of CTNNBIP1, namely A549, CL1-0, and CL1-5 cell lines." (PMID 31766223, 2019). "Our findings suggest that the CTNNBIP1 expression plays an important role in suppressing the β-catenin transactivation in lung cancer." (PMID 31766223, 2019). "Taken together, these results indicate that the CTNNBIP1 expression is able to affect the cell migration capacity of the various lung cancer cell model systems." (PMID 31766223, 2019). "The role of CTNNBIP1 in lung cancer proliferation should be investigated more thoroughly in later studies." (PMID 31766223, 2019). "Our results showed that treatment with 5-aza-dC successfully demethylated the promoter region of CTNNBIP1 gene, and in the process restored the mRNA and protein expression of CTNNBIP1 in all of the lung cancer cell lines." (PMID 31766223, 2019). "The CTNNBIP1 protein is important, in that it is able to control lung cancer cell migration via the coordinated regulation of the β-catenin pathway." (PMID 31766223, 2019). "In the present study, we provide the first compelling evidence that CTNNBIP1 is a suppressor of lung cancer progression." (PMID 31766223, 2019). "In the present study, we provided new evidence that the CTNNBIP1 expression is able to down-regulate the β-catenin transactivation, and that this inhibits the mobility of lung cancer cells." (PMID 31766223, 2019). "In order to identify the best cell models for further investigation, we performed Western blotting to detect the protein expression of CTNNBIP1 in four human lung cancer cell lines (A549, CL1-0, CL1-5, and H1299) and in one normal cell line (MRC5)." (PMID 31766223, 2019). "To further confirm the inverse correlation between the CTNNBIP1 expression and cell motility in lung cancer, we used siRNA to generate a knockdown of CTNNBIP1 in the H1299 lung cancer cell line." (PMID 31766223, 2019). "Together, these findings suggest that a low expression of CTNNBIP1 is a clinically relevant regulator of lung cancer that eventually leads to a poor prognosis." (PMID 31766223, 2019). "Our findings suggest that CTNNBIP1 is a suppressor of cancer migration, thus making it a potential prognostic predictor for lung cancer." (PMID 31766223, 2019). "To determine whether the promoter methylation of CTNNBIP1 is the predominant mechanism causing the loss of CTNNBIP1 expression to occur, we carried out a DNA methylation analysis of the CTNNBIP1 gene in four human lung cancer cell lines (A549, CL1-0, CL1-5, and H1299)." (PMID 31766223, 2019). "The aim of this study was to carry out a molecular analysis of CTNNBIP1 and its effect on β-catenin signaling, using samples from lung cancer patients and various lung cancer cell lines." (PMID 31766223, 2019).